RBP4 (retinol binding protein 4)
Diseases named in the same sentence as RBP4 in open-access papers (continued):
Sharing a sentence is not in itself a finding about the gene and the disease.
cardiovascular disease (continued). "However, recent findings point to a specific role of RBP4 in women as an independent predictor of cardiovascular disease, while a correlation has been reported between plasma RBP4 concentrations and cardiovascular risk factors, predominantly in young men." (PMID 24223837, 2013). "RBP4 level can be used as an index of cardiovascular disease risk in subclinical hypothyroidism." (PMID 19919702, 2009). "Future research will undoubtedly continue to unravel the intricate web of RBP4’s actions, potentially revolutionizing our approach to metabolic and cardiovascular diseases." (PMID 40276651, 2025). "Understanding RBP4’s mechanisms in these tissues is crucial for developing targeted therapies for metabolic and cardiovascular diseases." (PMID 40276651, 2025). "Among these, retinol binding protein 4 (RBP4) has been studied for its impact on cardiovascular disease." (PMID 36744248, 2023). "Retinol-binding protein 4 (RBP4) has been confirmed effects on vasodilation, platelet activation inhibition, and cardiovascular diseases by researches." (PMID 33505217, 2021). "Several other studies have shown that RBP4 concentrations were correlated with incident cardiovascular diseases." (PMID 33082885, 2020). "Past clinical studies have found a specific relation between elevated serum RBP4 levels and cardiovascular disease." (PMID 32635585, 2020). "Recently, a research conducted in patients with high risks of cardiovascular diseases has found that the level of RBP4 increased significantly." (PMID 30186876, 2018). "In our study we found an increased expression of RBP4 in diabetic patients with cardiovascular disease in regard to the others groups." (PMID 25923078, 2015). "The present study confirms that low adiponectin is associated with increased incidents of IHD, but not CVD, and suggests, for the first time, a major effect of visfatin, aFABP, and RBP4 in the development of cardiovascular disease." (PMID 21869928, 2012). "The aim of the study was to assess the relationship among adiponectin, RBP4, aFABP, and visfatin, and incident cardiovascular disease." (PMID 21869928, 2012). "RBP-4 is also considered an independent predictor of cardiovascular disease in women." (PMID 41303021, 2025). "Understanding the multifaceted roles of RBP4 could pave the way for novel interventions against metabolic and cardiovascular disorders." (PMID 40276651, 2025). "the receptor and signaling pathways by which RBP4 acts with endothelial cells and VSMCs deserve to be explored in further studies, which may contribute to the understanding of the RBP4 and cardiovascular disease linkage." (PMID 35309061, 2022). "In this review, we will focus on RBP4 and their implication in cardiovascular disorder." (PMID 35309061, 2022). "RBP4 may be involved in the development of cardiovascular disease by inducing an inflammatory response." (PMID 35309061, 2022). "Retinol-binding protein 4 (RBP4) is an adipokine correlated with cardiovascular diseases." (PMID 31278889, 2019). "However, the underlying role of RBP4 was still uncertain and the relationship between RBP4 and cardiovascular diseases remained controversial." (PMID 30186876, 2018). "The pathogenesis relationship between RBP4 and cardiovascular diseases was also studied." (PMID 28408942, 2017). "In parallel, RBP4 has exhibited modest heritability and sexual dimorphism (higher levels in men), while it is considered to represent a link between visceral adiposity and cardiovascular disease." (PMID 25142320, 2014). "The study of RBP4 antagonists may also be a new therapeutic agent for cardiovascular diseases." (PMID 35309061, 2022). "As such and most likely also via non-canonical functions, RBP4 is implicated in a variety of human conditions that include impaired vision and ocular diseases, disorders of glucose and lipid homeostasis, and cardiovascular diseases." (PMID 33790810, 2021).
cardiovascular disease (continued). "Given that an increasing number of human studies suggest that elevated plasma RBP4 levels may confer (subclinical) cardiovascular disease (CVD) risk, it is clinically relevant to more precisely delineate the association of RBP4 with various lipoprotein subfractions." (PMID 31717719, 2019). "Furthermore, regarding age and BMI distributions our population is likely to resemble conditions among prospective cohorts in which the relations of RBP4 and omentin-1 with the incidence of metabolic and cardiovascular diseases are likely to be investigated in future." (PMID 26402656, 2015). "RBP4 antagonists, such as BPN-14136, have demonstrated therapeutic potential in preclinical models of metabolic and cardiovascular disease, with more inhibitors currently being under evaluation." (PMID 41303567, 2025). "Retinol-binding protein 4 (RBP4) has emerged as a critical adipokine involved in the pathophysiology of metabolic and cardiovascular diseases." (PMID 40276651, 2025). "Serum RBP4, hs-CRP, and IL-27 play an important role in the occurrence and development of CHD, with a positive correlation to the Gensini score, which can indicate the severity of cardiovascular disease to a certain extent." (PMID 34956579, 2021). "The mean (SD) RBP4 concentrations were numerically but not significantly higher in those with and without established cardiovascular disease (2.39 (1.28) versus 1.77 (0.94) uM/l, p = 0.1)." (PMID 24651174, 2014). "The relationships between RBP4, aFABP, and visfatin, with respect to incident cardiovascular disease, have not been assessed, so far, in human models." (PMID 21869928, 2012). "This review summarizes the biological characteristics and multifunctional roles of RBP4 in CVD pathophysiology, examines its potential as a biomarker for diagnosis and prognosis, and explores its implications for developing new strategies to prevent and treat cardiovascular disorders." (PMID 41694300, 2026). "A clear cut-off value of RBP4 for cardiovascular diseases has not yet been set." (PMID 34758835, 2021). "Furthermore, plasma RBP4 concentration proved to be related to the presence of cardiovascular disease in non-obese, non-diabetic subjects." (PMID 25142320, 2014). "The present prospective study demonstrated higher RBP4 and lower adiponectin serum levels in patients with PAD undergoing endovascular revascularization than age- and sex-matched individuals without cardiovascular disease." (PMID 34758835, 2021).
metabolic disorders (42 papers, 2013 to 2026). "Aptasensors have been developed to detect metabolomic biomarkers, such as HbA1c, GHSA, RBP4, and others associated with metabolic diseases." (PMID 38137422, 2023). "Previous studies have shown that Linp1 is one of the key genes in adipogenesis, while RBP4 is elevated and associated with inflammation in metabolic diseases." (PMID 37022192, 2023). "We focused on the correlation of RBP4 with oxidative stress and inflammatory factors, both of which are established or proposed risk factors for metabolic disorders." (PMID 24559154, 2014). "RBP4, a vitamin A transporter, is linked to various metabolic diseases." (PMID 38275649, 2024). "Changes in RBP4 may be part of the metabolic disorder linked with AD and the inconsistent change between mouse models at 3 months in RBP4 transcript suggests that this may not be an early change in disease." (PMID 31884477, 2020). "Moreover, RBP4 has been implicated in lipid metabolism, contributing to metabolic disorders." (PMID 41144502, 2025). "Our findings contribute significantly to the limited data available on RBP4 levels in puberty, and thereby allow us to identify which age stage and degree of adiposity might determine RBP4-associated pathologic events and expand our understanding of the pubertal influences on metabolic disorders." (PMID 29759068, 2018). "Germacrone can reduce the lipid accumulation and metabolic disorders in hepatocytes by inhibiting the Nrf2-dependent expression of Rbp4." (PMID 40442809, 2025). "RBP4 signalling through these receptors (JAK/STAT pathway) has been associated with several inflammatory and metabolic diseases." (PMID 38275649, 2024). "In this context, inflammatory and metabolic diseases are complicated by the presence of molecules such as retinol-binding protein 4 (RBP4), TNF-α, and others that interfere with homeostasis." (PMID 37241737, 2023). "Liver-produced retinol-binding protein 4 (RBP4) is increased and associated with inflammation in multiple metabolic diseases." (PMID 36768465, 2023). "There has been strong evidence that shows that high levels of RBP4 have significant roles in the development of metabolic diseases and the induction of oxidative stress and inflammation." (PMID 37892122, 2023). "Growth, eyesight, and metabolic disorders are all impacted by RBP4, an adipokine mostly produced in the liver and fat." (PMID 35646102, 2022). "Although the precise mechanism is unclear, this finding suggests that any evaluation of the importance of RBP4 in metabolic disorders of children should take gender and puberty into account." (PMID 29759068, 2018). "A limited quantity of cross-sectional pediatric data exhibit an inconsistent relationship between RBP4 levels and childhood metabolic disorders, while prospective studies in youth remain scarce." (PMID 29759068, 2018). "Moreover, the impact of RBP4 on cardiac energy metabolism suggests a potential link between systemic metabolic disorders and heart failure, a connection that warrants further investigation." (PMID 40276651, 2025). "In conclusion, RBP4 is an important novel adipokine associated with many metabolic diseases; however, its potential mechanisms and effects have not been fully elucidated." (PMID 39698033, 2024). "Retinol-binding protein 4 (RBP4), an important protein in Vitamin A metabolism, have also been emphasized to be involved in the PCOS metabolic disorder and might be a diagnostic markers in PCOS." (PMID 39507894, 2024). "Due to the apparent links between RBP4 and metabolic disorders, correcting for BMI, fat deposition and urine albumin excretion may be key to elucidating genuine links between RBP4 levels and disease status." (PMID 34269526, 2022). "Changes in RBP4, STRA6 and CRBP1, associated with vitamin A’s role in metabolic disease may be linked with the metabolic abnormalities that occur in AD." (PMID 31884477, 2020).
metabolic disorders (continued). "However, their distinct correlations with various metabolic parameters, suggest that lipocalin-2 and RBP4 should have different patterns of regulation and there exists a complex interconnection between these two lipocalin proteins and metabolic disorders." (PMID 23799122, 2013). "The RBP4-induced shift toward type II fibers may contribute to reduced endurance capacity and increased fatigability, potentially exacerbating the physical limitations often observed in metabolic disorders." (PMID 40276651, 2025). "Therefore, kidney function has been proposed as a major determinant of serum RBP4 levels, which are known to deteriorate upon the onset of other metabolic diseases and thus may lead to an accumulation of RBP4 in the blood." (PMID 39698033, 2024). "Indeed, RBP4 is an important biomarker for several metabolic disorders." (PMID 31170218, 2019). "Thus, the association of RBP4 with systematic oxidative stress markers in humans may explain the possible mechanism of a high RBP4 status on metabolic disorders in humans." (PMID 24559154, 2014). "In PCOS, RBP4, an important protein in Vitamin A metabolism, has also been emphasized to be involved in the PCOS metabolic disorder." (PMID 39507894, 2024). "Additional research suggests that various other adipocytokines, including retinol-binding protein 4 (RBP4), lipocalin-2, omentin-1, vaspina, and others, might serve as potential biomarkers for assessing metabolic disorders." (PMID 40310144, 2025). "RBP4 may downregulate PGC-1α and affect transcription factors involved in fiber type specification, reducing oxidative capacity and impairing endurance, which may affect muscle performance and contribute to fatigue in metabolic disorders." (PMID 40276651, 2025).
cancer (41 papers, 2011 to 2025). A tumor composed of atypical neoplastic, often pleomorphic cells that invade other tissues. "RBP4 expression is closely associated with immune cell activity and immune-related molecules across a wide range of cancers." (PMID 40004479, 2025). "The underlying mechanisms through which RBP4 affects tumor behavior are still unclear, necessitating further investigation into its precise role in cancer progression." (PMID 41301068, 2025). "In this study, we analyzed the mRNA expression levels of RBP4 across 33 cancer types, along with its associations with cancer prognosis, immune-related factors, and DNA methylation." (PMID 40004479, 2025). "In recent years, studies have reported that RBP4 is associated with cancer, and it has a remarkable effect in promoting the migration and proliferation of ovarian cancer cells." (PMID 34889069, 2022). "While promoter demethylation is generally associated with gene activation, the downregulation of RBP4 in many cancers, despite the generally demethylated promoter, suggests that additional regulatory mechanisms may be involved." (PMID 40004479, 2025). "Additionally, RBP4 expression levels were positively correlated with the stroma score and immune score in most cancers, indicating their association with the tumor microenvironment." (PMID 40004479, 2025). "RBP4, a recently identified adipokine, has been associated with many types of cancer." (PMID 28924174, 2017). "Moreover, the association of STRA6 and RBP4 expression with metastasis, tumor recurrence, and therapeutic resistance suggests a role for these proteins in regulating cancer-initiating cells." (PMID 28689994, 2017). "A growing body of research has shown that RBP4 is associated with several types of cancer." (PMID 28002423, 2016). "Based on the availability of RBP4-related specimens and the significant differences in IHC staining in the HPA database, we selected two cancer types with elevated RBP4 expression and two with decreased expression for analysis." (PMID 40004479, 2025). "We analyzed the alteration status of RBP4 across pan-cancer using data from the cBioPortal database." (PMID 40004479, 2025). "The results showed that the expression level of RBP4 was upregulated in 6 types of cancer, namely, COAD, ESCA, PAAD, READ, STAD, and UCS, but it was downregulated in 21 other types of cancer compared with normal tissues." (PMID 40004479, 2025). "While several pan-cancer analyses of RBP4 have been conducted, such as those utilizing liver tumor cells or focusing on limited cancer types and datasets, our approach offers significant advantages." (PMID 40004479, 2025). "In conclusion, our pan-cancer analysis of RBP4 demonstrates its differential expression between tumor and normal tissues, highlighting associations with clinical prognosis and DNA methylation patterns." (PMID 40004479, 2025). "According to the database, the presumed copy-number alterations of RBP4 were identified through the Genomic Identification of Significant Targets in Cancer (GISTIC) analysis." (PMID 40004479, 2025). "The overall survival (OS), disease-specific survival (DSS), and progression-free interval (PFI) were selected to investigate the prognosis of RBP4 in pan-cancer." (PMID 40004479, 2025). "We leverage a broader range of cancer types from multiple comprehensive databases, and our study incorporates both in vitro and in silico analyses, providing a more holistic view of RBP4’s role in cancer progression." (PMID 40004479, 2025). "It has also been highlighted in recent studies that RBP4 is of critical importance in cancer cell metabolism." (PMID 40004479, 2025). "Our work confirmed the significant under expression of RBP4 in 21 cancers and overexpression of RBP4 in six cancers from the TCGA and GTEx databases." (PMID 40004479, 2025). "As of now, the majority of research has focused on the role of RBP4 in specific types of cancer, with limited exploration of its broader implications." (PMID 40004479, 2025).